GLIS2-AS1 (GLIS2 antisense RNA 1)
Gene: Long non-coding RNA gene on chromosome 16 (4,323,795 to 4,328,522, reverse strand). Ensembl gene ENSG00000262686.
Diseases named in the same sentence as GLIS2-AS1 in open-access papers:
GLIS2-AS1 is named in the same sentence as 1 disease in open-access papers, as found by Europe PMC text mining. Sharing a sentence is not in itself a finding about the gene and the disease.
GLIS2-AS1 shares sentences with these, for which no sentence is quoted: parathyroid carcinoma (1 paper).